CD44 (CD44 molecule (IN blood group))
Diseases named in the same sentence as CD44 in open-access papers (continued):
Sharing a sentence is not in itself a finding about the gene and the disease.
cancer (continued). "CD44 promotes the stemness of cancer stem cells through interactions with HA, extracellular matrix components, growth factors, and cytokines." (PMID 35936713, 2022). "CD44 is a cell-membrane embedded protein, and it interacts with different proteins to regulate cancer cell behavior." (PMID 36289750, 2022). "The present study results indicate that atropine modulates E-cad levels and reduces the gene and the protein levels of CD-44 and c-Myc that are upregulated after treating both cancer cell lines by TGF-β or carboplatin." (PMID 36077256, 2022). "NF-κB has been suggested to regulate CD44, SOX2, OCT4, and OILG2 expression in association with cancer cell invasiveness or stemness in different cancer models." (PMID 35906203, 2022). "Compared with the ubiquitous expression of CD44, CD44v is mainly expressed in cancer cells and correlated with CSC stemness, cancer metastasis, invasion, chemoresistance, and poor prognosis." (PMID 35504883, 2022). "For both types of NPs, regardless of size, faster and more intense internalization of HA-NPs in CD44+ CSC, hence CD44-HA interactions can be considered an excellent vehicle to improve the efficiency of anti-cancer drugs against CSC." (PMID 36091467, 2022). "Frequency of CD44+ cells and expression levels of Cd44 and other cancer stem cell markers Ascl2, Lgr5 and Smoc2 were markedly reduced in Mex3a-deficient tumors." (PMID 36276637, 2022). "Of note, KIT+, ALDH1+ and SOX2+ cancer stem cell populations harbor proliferative and epithelial-like characteristics, while CD44+ and SOX9+ cancer stem cell populations demonstrate invasive and mesenchymal-like properties." (PMID 36171192, 2022). "CD44/ITGB1 based sorting of the A431 cell line also identified a subset within the cancer stem cells (CSC) that display EMT characteristics." (PMID 35666359, 2022). "It is also well-documented that CD44 promotes cancer cell migration and invasion via mesenchymal markers." (PMID 36289750, 2022). "An in vitro cancer-targeting efficiency of synthesized core-shell nanoparticles was tested with both CD44 high expressing (MDA-MB 231 cells) and CD44 low expressing cells (NIH3T3 cells) using confocal laser scanning microscopy." (PMID 36046728, 2022). "Results from our scRNA-seq analyses identified several potential interactions involving the cancer stem cell marker CD44 with ligands secreted by CAFs such as HGF, HBEGF, FGF2 and LGALS9." (PMID 36273171, 2022). "CD44 is also a member of cell surface glycoprotein family, which is closely related to the proliferation, adhesion, and metastasis of cancer cells." (PMID 35470736, 2022). "A recent study showed that downregulating the HIF-1α/NOTCH-1 pathway was able to eliminate CD44+ cancer stem-like cell phenotypes to enhance the malignancy and chemo-resistance in neck squamous cell carcinomas." (PMID 36358852, 2022). "On the basis of these findings, oligosaccharides show potential to suppress other physiological responses related to CD44, especially the proliferation and migration of cancer cells promoted by CD44." (PMID 35215410, 2022). "Cumulative evidence indicates CD44 is not only a cancer stem cell marker but also a critical regulator of cancer stemness." (PMID 36292918, 2022). "Several peptides and RNA aptamers directed against CD44 have already been tested in many cancer models." (PMID 35785191, 2022). "As CD44 is a hallmark for cancer stemness in a number of cancers, including OSCC, we further examined the ability of cancer stem cell-like growth in OSCC cells under the influence of differential MRE11 expression levels." (PMID 35629265, 2022). "Still, few studies have addressed the CD44 glycocode in cancer and its functional implications for disease progression 25-27." (PMID 35547758, 2022). "In 2015, Transmembrane 4 six family members 5 (TM4SF5) was found to bind and interact with CD44, thus improving the self–renewal properties of cancer cells and subsequently promoting the metastatic potential of CTCs." (PMID 36059616, 2022).
cancer (continued). "Through downregulation of the Fas-FasL pathway via CD44, cancer cells can reportedly escape the killing of cytotoxic T lymphocytes (CTLs)." (PMID 36588538, 2022). "These PGCC-derived tumors gained a mesenchymal phenotype with increased expression of the cancer stem cell markers CD44 and CD133." (PMID 35955416, 2022). "These biosensor characteristics represent a promising new way of detecting the important CD44 biomarker in cancer diagnostics." (PMID 36421133, 2022). "CD44 is a common surface marker of cancer stem cells and it plays critical roles in the regulation of stemness and metastasis." (PMID 35223528, 2022). "In further experiments, we found that inhibition of miR-328-3p dramatically increased the proportion of CD44 + CD24-cells (cancer stem-like cells)." (PMID 34045663, 2022). "CD44 have functions in many processes in normal cells (hematopoietic, immune system, and organogenesis), and in pathological situations (inflammation and cancer)." (PMID 35628345, 2022). "Pharmacological inhibition of NF-κB downregulates CD44 expression, thereby decreasing cancer cell proliferation and invasiveness." (PMID 36605595, 2022). "We found that plasticity, which re-programmed CD44(-) differentiated cancer into CD24(+)CD44(+)EpCAM(+) CICs, was inhibited when JAG1 was neutralized." (PMID 35673567, 2022). "By downregulating integrins and CD44 of cancer cells, as well as E-selectin of endothelial cells, component G inhibited invasion and migration of cancer cells." (PMID 36184654, 2022). "First, performed staining against the stem cell marker CD44.a transmembrane glycoprotein that is overexpressed in several cancers." (PMID 35844581, 2022). "Cancer Stem Cells (CSCs) that express CD44+/CD24- can contribute to chemoresistance and a poor prognosis." (PMID 36274112, 2022). "In this study, we first observed that the highly expressed CD44 (CD44high) cancer cell clusters were located in the BrCa circulating vessels, accompanied by CD206+ TAMs." (PMID 35680853, 2022). "Next, we examined the level of a well-known cancer stem cell (CSC) marker CD44 mRNA by qRT-PCR in chemoresistant (n = 13) and sensitive (n = 11) HNSCC patients’ samples." (PMID 35945195, 2022). "Due to HA’s targeting of CD44 and its characteristics, the nanodelivery system can target CD44-overexpressing cells and avoid unexpected release; at the same time, it can target cancer cells." (PMID 35456573, 2022). "In human glioblastoma multiforme, CD44 enhanced the cancer stem cell phenotypes and promoted therapeutic resistance, whose expression level was correlated with a poor survival rate." (PMID 36292918, 2022). "CD44, an essential transmembrane glycoprotein and extracellular matrix receptor, is also a cancer stem cell marker." (PMID 35453596, 2022). "CD44 constitutes an additional appealing molecular candidate for anti-cancer targeted drug delivery." (PMID 35205658, 2022). "In our current study, the primary objective was to investigate the occurrence of rare cancer cells based on the specific binding of QDAb for the EpCAM+ and EpCAM− (CD44+ and CD45 +) cell lines in-vitro based peripheral blood mimic sample co-culture models." (PMID 35393460, 2022). "The effects of TAZ knockdown on apoptosis rate, stemness, and cancer stem cell (CSC) marker (CD44, OCT4, and ALDH1A) levels in A2780/DDP and DDP-treated A2780/DDP cells were assessed." (PMID 36247876, 2022). "NETs enhance the expression of EMT markers ZEB1, Snail and fibronectin, cancer stem cell marker CD44, proinflammatory mediators, such as IL1β, IL6, IL8, CXCR1, MMP2 and MMP9." (PMID 35574410, 2022). "CD44 regulates diverse vital signaling pathways that modulate cancer proliferation, invasion, metastasis, and therapy." (PMID 35845934, 2022). "The Transwell assay illustrated that knockdown of CD44 or SPP1 notably prevented cancer cell migration." (PMID 35790930, 2022).
cancer (continued). "HOXB9 alters cancer stem cell markers, such as CD44, and affects chemosensitivity and metastatic ability of ALDHhigh/CD44+/CXCR4+/CD24+ PCSCs." (PMID 36300093, 2022). "MNCD/HA and doxorubicin (DOX), an anthracycline antitumor antibiotic used in chemotherapy for several types of cancers of the lung, breast and ovaries, resulted in efficient detection of mouse melanoma (B16F1) cancer cells overexpression by CD44." (PMID 36364403, 2022). "The biomarker CD44, which is expressed in many types of cancer, is an adhesion receptor that regulates the process of metastasis on the cell surface." (PMID 36421133, 2022). "Cell surface glycoprotein CD44 has been widely studied as a potential biomarker of BC aggressiveness and cancer stem cells." (PMID 35547758, 2022). "The biomarkers that are used to isolate and identify putative CSC populations vary from cancer to cancer, but among the most common are CD44 and CD133, although some controversy remains." (PMID 36091174, 2022). "CD44 is a transmembrane glycoprotein typically expressed by immune cells, bone marrow mesenchymal cells, embryonic stem cells, and cancer stem cells." (PMID 35386200, 2022). "This study revealed that 4-MU enhanced intracellular oxidative stress and suppressed the expression of cluster-of-differentiation (CD)-44 and cancer stem cell (CSC)-like phenotypes." (PMID 36497040, 2022). "The part-time proteoglycan CD44 is detectable on the surface of tEVs from multiple cancer cell types where it has been reported to mediate the acquisition of cancer-associated phenotypes by mesenchymal cells." (PMID 36106109, 2022). "These CD44+/CD24− cells show cancer stem-like cell (CSC) characteristics, such as radiation resistance, enhanced self-renewal potential, differentiation capacity, and a superior generation of tumors in animal hosts." (PMID 35406578, 2022). "In a very recent work, PLGA-based nanoparticles were functionalized with hyaluronic acid of different weights (200, 800, and 1437 kDa) and their targeting properties were evaluated on CD44-overexpressing cancer cells." (PMID 35626078, 2022). "Using the CRISPR/Cas9 technique, it is possible to target stem cell markers such as NANOG1, NANOGP8, and CD44, which can lead to a significant attenuation of drug resistance in cancer cells." (PMID 35715750, 2022). "Monoclonal antibody labeled with indium-111 that targets CD44 and had been suggested the possible use in the detection of this cancer." (PMID 35785191, 2022). "Upon selective binding to CD44-expressing cancer cells, nanoparticles underwent endocytosis, and the hyaluronic acid coating was degraded in the lysosomal compartment." (PMID 35626078, 2022). "More interestingly, EGFR can enhance the CD44–mediated cancer cells aggregation and CD44 can stabilize EGFR in turn." (PMID 36059616, 2022). "Cell uptake experiments confirmed the CD44-mediated internalization of nanoparticles in cancer cells, while the apoptotic mechanism of cell death, typical of doxorubicin treatment, was confirmed by comet assay." (PMID 35216501, 2022). "We next evaluated CD44 expression by flow cytometry in both CD109 KO and control A431 cells, as CD44 is a cancer stem cell (CSC) marker that is involved in the regulation of CSC survival, self-renewal, and metastatic colonization." (PMID 35954339, 2022). "A study advocated that a cross-talk between MDSCs and CSCs drives cancer progression, such as CD44+ stem-like cells promote regulatory T cells and inhibit T cell proliferation compared to CD44 stem cells." (PMID 36550571, 2022). "Similar to HA, CS has a great targeting ability for the cluster CD44, which is overexpressed in particular cancer cells." (PMID 36432183, 2022). "Previous studies have shown the roles of CD44 as prognostic factors and therapeutic targets in human cancers." (PMID 35229451, 2022). "We also tested expression of Bcl2, which is an important anti-apoptotic factor previously correlated with CD44 expression in other human cancers." (PMID 35955749, 2022).
cancer (continued). "These HA–NPs enhanced the cellular uptake and cytotoxicity in two cell lines of pancreatic ductal adenocarcinoma, highlighting the effect of HA on targeting CD44 overexpressed in cancer cells." (PMID 36297526, 2022). "Further, CD44 is an important marker of cancer stem cells, and several studies have previously highlighted the involvement of miR-29a-3p in cancer stem cell proliferation and differentiation." (PMID 36499093, 2022). "We observed a transient increase in CTNNB1 and a sustained increase in CD44, a cancer stem cell marker downstream of CTNNB124,25." (PMID 35906361, 2022). "Increased CD44 expression on circulating cancer cells enhances the “efficiency of post-intravasation events and distant metastasis in vivo, consistent with its association with increased distant recurrence and reduced disease-free survival in patients”." (PMID 35903297, 2022). "It is widely known to specifically bind with cluster determinant 44 (CD44) that is over-expressed in many different types of cancer cells, including ovarian cancer cells (SK-OV3) and colon cancer cells (CT26)." (PMID 35387175, 2022). "Previous reports have shown that EMP1 can regulate CD44 expression in glioma stem cells, resulting in promoting of cancer cell stemness." (PMID 36217151, 2022). "BCSCs were identified as a rare population of cancer cells of a CD44+CD24−/lowLin− phenotype that possessed higher tumor initiation capacity than BC cells of a different phenotype." (PMID 35530300, 2022). "We first measured the gene expression of cancer stemness-related factors, including CD44, CD133 and SOX2, which are major stemness markers of PCA." (PMID 35365766, 2022). "CD44 is a transmembrane glycoprotein that is expressed in most cell types, and is a receptor for hyaluronic acid and a marker of cancer stem cells, which is upregulated by NF-κB." (PMID 35625673, 2022). "CD44 is both considered to be a mesenchymal marker gene and also a marker gene for cancer stem cells." (PMID 36358747, 2022). "Their group demonstrated that cancer cells with the CD44+ CD24−/low phenotype had a greater tumorigenic capacity when transplanted into immunodeficient mice (NOD/SCID), compared to those cells that did not have this phenotype." (PMID 35954194, 2022). "Since several studies have shown that the stemness of TNBC (CD44 + /CD24−) is also an important property for cancer progression." (PMID 36280829, 2022). "Previously, it has been reported that CD44 is a cancer stem cell marker, and stem cells usually display drug resistance." (PMID 36289750, 2022). "Compared with PD-1 inhibitor group, ki-67 proliferation index and CD44 expression of cancer cells in the chimeras/AuNP-CM group were further significantly decreased." (PMID 36082168, 2022). "Cancer cells overexpressing the cell surface protein CD44 were targeted with HA nanoparticles containing siRNA against ABCB1." (PMID 36091772, 2022). "CD44v3 (CD44v3–v10), containing CD44 variable exons 3–10, has been confirmed to play an important role in the proliferation of various types of cancer cells." (PMID 36527033, 2022). "These molecules mediate a cross-talk between hyaluronan-CD44 signaling in cancer cells to maintain the stemness in cancer cells." (PMID 36550571, 2022). "In contrast, lipid raft disruption by depleting cholesterol prevents CD44 from recruiting to lipid rafts, enhances CD44 shedding, and suppresses CD44-dependent cancer cell migration." (PMID 36042526, 2022). "CD44 has been used as a marker of cancer-initiating cells in various cancers, including prostate, pancreas, and colon." (PMID 35742872, 2022). "Sam68 retains a heteronuclear ribonucleoprotein particle K homology (KH) domain to control the alternative splicing of several cancer-related gene transcripts, including Bcl-x, Cyclin D1, CD44, SF2/ASF, and Survivin." (PMID 35217791, 2022).
cancer (continued). "The interaction of fibronectin with CD44 facilitates the extravasation of cells and the adhesion processes, allowing cancer cells to adhere more efficiently to ECM within a metastatic microenvironment." (PMID 35785191, 2022). "By binding to ezrin, radixin and moesin proteins, CD44 can bind to the cytoskeleton with the cell membrane, which facilitates cancer cell growth and metastasis." (PMID 35719973, 2022). "CUR was conjugated as an ester to CHA (CHA-CUR) to prepare the NGs for the targeted delivery of Cur to CD44-expressing MDR cancer cells." (PMID 36559325, 2022). "Metformin has been shown to radiosensitize cancer cells and predominantly eradicate CSCs by the downregulation of genes, such as CD44 and EPCAM or by the inhibition of EMT." (PMID 35269569, 2022). "The expression of CD44 is higher in drug-resistant cancer cells than in drug-sensitive cancer cells." (PMID 35814435, 2022). "In this setting, we observed that IFN-I favors the enrichment of rare CD133+CD24+CD44+ putative CSCs (IFN–CSCs) in all analyzed murine cancer cell lines." (PMID 36002648, 2022). "CD44, a well-established CSC marker, is necessary to initiate EMT and is linked to cancer treatment resistance and poor outcome." (PMID 35053979, 2022). "First, we used QPCR to detect several commonly used biomarkers of cancer stem cells, which are CD44, EpCAM, SOX2, C-MYC." (PMID 35816352, 2022). "Antibodies targeting CD44 are being tested in preclinical and clinical trials for many types of cancer." (PMID 35785191, 2022). "The activation of this signaling cascade was correlated with enhanced OSCC cancer stemness and elevated expression of CD44 and epidermal growth factor receptor (EGFR)." (PMID 35706019, 2022). "Various signaling pathways are indirectly stimulated by the interaction between HA and receptor CD44, which promotes cancer progression as well as the transcription of pro-oncogenic genes." (PMID 36613567, 2022). "Our study also opened a new field that chemotherapy such as gemcitabine or paclitaxel tends to enrich CD44-positive cells, especially CD44s isoform in various cancer types." (PMID 35931675, 2022). "Monoclonal antibodies that recognise the C‐terminus of PTX3 and disrupt the interaction between PTX3 and CD44 were developed to validate the PTX3/CD44 axis‐induced protumour effects on cancer development, metastasis/invasion and stemness." (PMID 35090088, 2022). "This section discusses six shedding examples that influence cancer progression, namely, CD44, ICAM-1, DDRs, syndecans, EphA2, and HB-EGF." (PMID 36132127, 2022). "CD44 was first identified on lymphocytes and is overexpressed in several cell types, including cancer stem cells." (PMID 35790930, 2022). "CD44 and its isoforms are overexpressed in various cancer types and are crucially involved in cancer development by interacting with certain ligands such as hyaluronic acid and osteopontin." (PMID 36293491, 2022). "Meanwhile, 1-MNA reduced the ubiquitin-mediated degradation of CD44 and stabilized CD44 protein, promoting cancer cell invasion and migration." (PMID 35756670, 2022). "Among the list of proteins, standard CD44 was preferentially chosen because CD44 has been recognized as a critical regulator of cancer metastasis." (PMID 35359362, 2022). "Of note, Sam68 interacts with the splicing activator SRm160 promoting inclusion of v6 exons in CD44 (CD44v6), a marker of metastatic cancer stem cells (CSCs)." (PMID 35217791, 2022). "In our previous study, we noted that human SF and ESF express higher levels of CD44 mRNA than cattle and the knockdown of CD44 transcripts in human cells make them less invasible by cancer and trophoblast cells." (PMID 36148042, 2022). "As a result, the appearance of the standard form of CD44, CD44s, which in this context increases the migratory power of cancer cells." (PMID 35406498, 2022). "HA-mExo-miR204 was able to specifically target CD44-positive cancer cells, with a concomitant increase in miR-204 intracellular uptake." (PMID 36231028, 2022).